CCR3 (C-C motif chemokine receptor 3)
Diseases named in the same sentence as CCR3 in open-access papers (continued):
Sharing a sentence is not in itself a finding about the gene and the disease.
Alzheimer disease (5 papers, 2016 to 2024). A progressive, neurodegenerative disease characterized by loss of function and death of nerve cells in several areas of the brain leading to loss of cognitive function such as memory and language. "CCL11 is a ligand for the chemokine receptor type 3 (CCR3) receptor and, thus, CCR3 has been identified as a potential therapeutic target for Alzheimer’s disease that reduces amyloid beta deposition and tau phosphorylation." (PMID 37280551, 2023). "Interestingly, a previous study of an Alzheimer’s disease model has shown a link between reduced cell surface CCR3 and reduced microgliosis, in line with our results." (PMID 37285551, 2023). "Expression of CCR3 is elevated in the setting of human immunodeficiency virus infection, and elevated expression of CCR3 is observed in reactive microglia and astrocytes around the amyloid deposits in Alzheimer’s disease." (PMID 27822494, 2016). "Immunohistochemical study of the β-chemokine receptors CCR3 and CCR5 and their ligands in normal and Alzheimer’s disease brains." (PMID 31447666, 2019).
glioma (5 papers, 2016 to 2023). A benign or malignant brain and spinal cord tumor that arises from glial cells (astrocytes, oligodendrocytes, ependymal cells). "MFAP2 expression was also correlated with chemokine receptors in gliomas, such as CCR3, CCR7, CXCR4, and CXCR6, which were significantly associated with MFAP2 expression in both LGG and GBM." (PMID 36204318, 2022). "CCL11 and its principal receptor CCR3, is another chemoattractant candidate that appears to be involved in the migration of glial tumor cells." (PMID 34830041, 2021). "Expression of CCL11 and CCR3 was also examined in normal human astrocytes (NHA) and three different glioma cell lines (U251MG, U87MG and A172)." (PMID 27119233, 2016). "In addition, the levels of CXCL9, CXCL10, and CCR3, which increase the recruitment of CD8+ T cells into the microenvironment of glioma, were increased in gliomas with high TANK expression." (PMID 37215097, 2023). "Studies have demonstrated that GAMs were recruited to sites of gliomas via interaction between CCL2/MCP-1 which are basically generated by glioma cells as well as its receptor CCR2 which is secreted by GAM and by a CCL7/MCP-3-CCR1/CCR2/CCR3-crosstalk." (PMID 35419058, 2022). "Interestingly, the expression of CCR3 in lower-grade gliomas did not change significantly, suggesting different mechanisms were involved in the progression of GBM and lower-grade gliomas." (PMID 27119233, 2016).
lung fibrosis (5 papers, 2016 to 2024). "In the periphery, CCR3 plays significant pathogenic roles in the development of inflammation, allergic reactions, and lung fibrosis." (PMID 27822494, 2016). "Moreover, it was found that high expression levels of CCR3 are associated with worse survival outcomes in patients with pulmonary fibrosis." (PMID 35625754, 2022).
melanoma (5 papers, 2013 to 2024). A malignant, usually aggressive tumor composed of atypical, neoplastic melanocytes. "In a recent comprehensive study, melanoma cells were shown to express a whole set of chemokine receptors, including CCR3, CCR4, CXCR3, CXCR7, CX3CR1 and membrane CX3CL1." (PMID 23344048, 2013). "Moreover, the CCR3 was overexpressed in biopsies from patients with malignant melanoma." (PMID 34068679, 2021). "Melanoma cell lines overexpress CCL5 and have decreased levels of CCR1, CCR2, and CCR3." (PMID 34068679, 2021). "Additionally, a tendency toward lower CD31 (p = 0.09) and CCR3 expression (p = 0.10), and higher CD69 (p = 0.07) and CD29 expression (p = 0.15) was observed on neutrophils from late-stage melanoma patients compared to healthy donors, which were all not statistically significant." (PMID 38730718, 2024).
multiple sclerosis (5 papers, 2017 to 2025). A progressive autoimmune disorder affecting the central nervous system resulting in demyelination. "Inhibition of CCR3 is expected to provide a robust therapeutic approach for the treatment of aging-associated neuroinflammatory diseases, particularly those associated with excessive T-cell infiltration such as multiple sclerosis and Parkinson’s disease." (PMID 36934154, 2023).
autoimmune disease (4 papers, 2017 to 2023). A disorder resulting from loss of function or tissue destruction of an organ or multiple organs, arising from humoral or cellular immune responses of the individual to their own tissue constituents. "MCP-4 is a chemokine known for its affinity to CCR3, and it has been implicated in autoimmune diseases like RA as well as allergic conditions." (PMID 38274820, 2023). "While CCL28 is responsible for the recruitment of various immune cells (which express CCR10 and CCR3) for mucosal tissue and inflammatory sites, some data indicate that it is responsible for recruiting Treg, maintaining tolerance of self antigens and preventing autoimmune diseases." (PMID 33139632, 2020). "RANTES, an inflammatory chemokine that has receptors, including CCR1, CCR3, and CCR5, can recruit immune cells to inflammatory sites and is involved in autoimmune diseases." (PMID 36173680, 2022).
emphysema (4 papers, 2004 to 2021). "Moreover, the expression of both eotaxin-1 and CCR3 is up regulated during exacerbations of chronic bronchitis and eotaxin-1 levels are associated with bronchodilator response and the extent of emphysema on CT scans." (PMID 19925666, 2009). "The loss of lung function in patients with COPD and emphysema is associated with a high percentage of CD4+ and CD8+ T lymphocytes that express receptors CCR5 and CXCR3, but not CCR3 or CCR4 (both markers of T helper one cells)." (PMID 33953665, 2021). "Flow cytometry revealed very low expression of CCR3 and CCR4 (1%–3%) in control (n = 10) and emphysema (n = 18) groups, and did not discriminate between these populations (data not shown)." (PMID 15526056, 2004).
glioblastoma (4 papers, 2016 to 2025). The most malignant astrocytic tumor (WHO grade IV). "The processes of many pathological states such as Crohn's disease, neurodegenerative disease, glioblastoma 32 and eosinophilic myocarditis 33 involve CCR3 signalling." (PMID 33511766, 2021). "Tian et.al (2016) showed that CCR3, was overexpressed and that CCL11/CCR3 signaling promoted the proliferation, migration and invasion of glioblastoma cells." (PMID 40484866, 2025).
HIV-1 infection (4 papers, 2009 to 2017). The type species of lentivirus and the etiologic agent of acquired immunodeficiency syndrome (AIDS). "Microglia are the major target cell type for HIV-1 infection in the CNS, with CCR3 and CCR5 providing the port of entry for macrophage-tropic viruses." (PMID 27873219, 2017). "Besides, it is possible that MDMis exposed to LTs show attenuated levels of other surface molecules known to play a role in HIV-1 infection in the CNS, such as CCR3 or galactocerebroside (or galactosylceramide)." (PMID 22424294, 2012). "Genomic scan analyses have suggested that the chemokine receptor cluster (CCR2, CCR3, CCR5 <300 kb span) on the short arm of chromosome 3 may contribute to susceptibility to HIV-1 infection and to the expression of a number of inflammatory diseases." (PMID 20220260, 2010).
malaria (4 papers, 2005 to 2017). Malaria is a serious and sometimes fatal disease caused by a parasite that commonly infects a certain type of mosquito which feeds on humans. "The expression levels of CXCL10 (5.3-fold) was highest during the early phase of malaria, while CCR3 and CCL4 were higher during febrile and recovery stages of the disease." (PMID 24188121, 2013). "We also found these regulatory markers are in strong LD (r2>0.75) and carriage of the resultant haplotype TTR2 with asymptomatic and CCR3 with malaria cases (OR = 0.552, 95%CI = 0.356–0.854, p = 0.009)." (PMID 23110190, 2012). "The upregulation of RANTES, CCR1, CCR3, and CCR5 mRNA, and RANTES protein mediate inflammation and cellular degradation in the cerebellum during P. yoelii 17XL malaria." (PMID 16359553, 2005). "The hypothesis of this study is that RANTES and its corresponding receptors (CCR1, CCR3 and CCR5) modulate malaria immunopathogenesis." (PMID 16359553, 2005).
parasitic infection (4 papers, 2012 to 2023). "We believe that this increase could be possibly related to the increased expression of Ccr3 in response to KO parasite infection or exosome treatment, as we were able to detect it by qRT-PCR." (PMID 24736445, 2014). "CCL24 is a specific agonist for CCR3, attracting and activating eosinophils in parasitic diseases." (PMID 22506080, 2012).
renal cell carcinoma (4 papers, 2016 to 2024). "For instance, CCR3/eotaxin-1 loop has been revealed to increase the growth of malignant tumor cells in T-cell lymphomas, and the presence of CCR3 in human renal cell carcinoma samples correlates with the grade of malignancy." (PMID 27086913, 2016). "CCR3 ligand may be up-regulated by tumour-related inflammation and involved in the progress of renal cell carcinoma, whereas the CCR3/eotaxin-1 loop could induce malignant cell growth in T-cell lymphomas." (PMID 35574316, 2022). "In renal cell carcinoma, CCR3 facilitates tumor proliferation and metastasis through the CCL11/CCR3 axis." (PMID 38511143, 2024).
Stroke (4 papers, 2016 to 2024). Sudden impairment of blood flow to a part of the brain due to occlusion or rupture of an artery to the brain. "In stroke research, CCR3 has been implicated as a mediator of neuronal injury after ischemic insult." (PMID 38332938, 2024). "The study identified an association between CCR3, related genes, and type 2 diabetes mellitus as predictors for stroke outcomes." (PMID 38332938, 2024). "In particular, microbleeds residing outside of the infarct area are associated with VCID pathogenesis, Microbleeds found in rat brains after the stroke procedure in this study are associated with increased CCR3 expression." (PMID 38332938, 2024). "Our group previously reported that CCR3 expression is significantly associated with infarct volume and edema in stroke patients undergoing thrombectomy." (PMID 38332938, 2024). "Expression of CCR3 signaling genes in our rat model of thrombectomy reflects a similar pattern to the data retrieved from human stroke patients, indicating that the expression of these genes is associated with increased stroke-induced damage to the brain." (PMID 38332938, 2024). "Previously, we have reported that CCR3 is a significant predictor for both infarct volume and edema in stroke patients undergoing thrombectomy." (PMID 38332938, 2024). "The expression of C-C motif chemokine receptor 3 (CCR3) has been reported to increase after experimental stroke, and the inhibition of CCR3 has been demonstrated as a protective factor for neurons after an ischemic event." (PMID 38332938, 2024). "Using an in vivo model of stroke, our study aims to link CCR3 expression with endothelial dysfunction in this rodent stroke model." (PMID 38332938, 2024). "Our results demonstrate that CCR3 expression is increased 30 days after stroke in areas of microbleeds in our animal model that mimics patients undergoing thrombectomy." (PMID 38332938, 2024). "Using linear regression, we found that increased expression of CCR3 and its ligands after stroke were positively correlated with infarct volume." (PMID 38332938, 2024). "We have determined that CCR3 expression is increased in venous blood in our rat stroke model and patients undergoing thrombectomy." (PMID 38332938, 2024). "The seven important predictor genes (CCR4, IFNA2, IL-9, IL-7, IL-5, CCR3, and IL-27) that overlapped both stroke outcomes had mean fold change ranging from 3.98 to 35.06." (PMID 32010048, 2019). "So CCR3-/- mice showed smaller infarction and less neurological deficits via reducing the neuronal death or regulating the inflammation after stroke?" (PMID 27822494, 2016). "Thus, future studies should continue to determine the impact of CCR3 signaling on cognitive and functional outcomes after stroke to determine if it is a therapeutic target to reduce stroke induced detrimental effects." (PMID 38332938, 2024). "CCR3 expression staining significantly increased following stroke at 30 days (p <0.001)." (PMID 38332938, 2024). "CCR3 has been reported to increase after experimental stroke and in human stroke patients." (PMID 38332938, 2024). "Thus, CCR3 antagonists are a logical next step to investigate the vascular permeability that leads to cognitive impairment in future animal models of stroke." (PMID 38332938, 2024). "Inhibiting CCR3 may also have additional beneficial effects after stroke by diminishing the Th2 response." (PMID 38332938, 2024). "Our results demonstrate that CCR3 expression is associated with the presence of microbleeds at 30 days but not 3 days post-stroke in the ipsilateral hemisphere, and further supports the link between CCR3 and the endothelial dysfunction that is associated with VCID." (PMID 38332938, 2024). "Our group has previously reported that, when using machine learning analysis, CCR3 expression was a predictor of both infarct and edema volumes, while CCL11 was a predictor of edema volume from the blood of human stroke patients." (PMID 38332938, 2024).
Stroke (continued). "The intersection of the top 10 genes from the two stroke outcomes are seven genes with T2DM, these include CCR4, IFNA2, IL-9, IL-7, IL-5, CCR3, and IL-27." (PMID 32010048, 2019). "CCR3 and Prussian blue staining significantly increased in rat brain sections following stroke at 30 days, but not at 3 days, and co-staining with CCR3 and vWF antibodies demonstrated overlapping expression." (PMID 38332938, 2024). "CCR3 signaling has previously been associated with endothelial permeability in AMD, but not in stroke." (PMID 38332938, 2024). "The expression of ligands for CCR3, CCL5, CCL11 and CCL24, have been studied in stroke models." (PMID 38332938, 2024). "Thus, after antagonizing the chemokine receptor CCR3 in adolescent stroke mice, acute brain injury was not affected by SB297006." (PMID 31888056, 2019).
viral infection (4 papers, 2013 to 2023). "These chemokines include SDF-1α, MCP-2, MCP-4, MIP-1α, and Eotaxin-1, which bind either to CXCR4, CXCR5, CCR5, or CCR3 and regulate viral infection." (PMID 36851142, 2023).
AIDS (3 papers, 2011 to 2020). A syndrome resulting from the acquired deficiency of cellular immunity caused by the human immunodeficiency virus (HIV). "Significant associations with differential progression to clinical AIDS were observed for CCR3 -255C (RH = 0.62, P = 0.009), for CCRL2-243V (RH = 0.66, P = 0.03), and for CCRL2-167F (RH = 1.89, P = 0.0003) and for CCR8-27G (RH = 1.44, P = 0.004)." (PMID 22046140, 2011). "Genotypes of exonic polymorphisms in chemokine coreceptor genes CCR3, CCRL2 and CXCR6 on Chromosome 3p21 and in CCR8 and CX3CR1 on 3p22 were tested for their genetic influence on AIDS progression." (PMID 22046140, 2011). "In addition to the known CCR5 and CCR2 associations, significant associations were identified for CCR3, CCR8, and CCRL2 on progression to AIDS." (PMID 22046140, 2011).
airway hyperresponsiveness (3 papers, 2017 to 2022). "CCR3 mRNA and protein levels are elevated in the bronchial mucosa of asthmatics, and this enhanced expression is associated with airway hyperresponsiveness." (PMID 29062168, 2017). "IVE and AET ameliorated OVA-driven airway hyperresponsiveness (p < 0.01), pulmonary eosinophilic infiltration (p < 0.05), mucus hypersecretion (p < 0.01), and IL-4, IL-5, IL-13, and CCR3 production (p < 0.05), as well as IgE levels (p < 0.01)." (PMID 29062168, 2017).
anaplastic large cell lymphoma (3 papers, 2017 to 2024). Anaplastic large cell lymphoma (ALCL) is a rare and aggressive peripheral T-cell non-Hodgkin lymphoma, belonging to the group of CD30-positive lymphoproliferative disorders, which affects lymph nodes and extranodal sites. "The interaction between CCL11 and CCR3 enhances the survival of anaplastic large cell lymphoma cells via ERK1/2 activation." (PMID 38305920, 2024). "Miyagaki found that CCR3 was associated with anaplastic large cell lymphoma (ALCL) cells via ERK1/2 activation; CCR3 played a role in the recruitment and retention of CD30+ malignant T cells to the skin in skin-specific cutaneous T-cell lymphoma (CTCL)." (PMID 28042950, 2017).
diabetes (3 papers, 2023 to 2025). "Previous studies have reported that CCR3 was upregulated in diabetes patients." (PMID 37457235, 2023). "CCL5 interacts with several chemokine receptors, such as CCR1, CCR3, and CCR5, to mediate its effects, extending to various pathological conditions, including inflammatory diseases, cancer, and metabolic disorders like diabetes." (PMID 39807180, 2025).
gastric cancer (3 papers, 2016 to 2025). A primary or metastatic malignant neoplasm involving the stomach. "PPI network analysis highlighted eight key hub genes (CD80, CCR9, CXCR3, CXCR5, CXCR6, CCR3, CCL20, and CXCL1), revealing their pivotal roles in gastric cancer and H. pylori infection." (PMID 40445003, 2025).
lung adenocarcinoma (3 papers, 2016 to 2024). A carcinoma that arises from the lung and is characterized by the presence of malignant glandular epithelial cells. "Thus, we examined the expression of CCR3/CCR10 on various tumor stromal cells, revealing widespread expression of CCR3 on endothelial cells, cancer-associated fibroblasts, and pericytes in lung adenocarcinoma." (PMID 39075504, 2024). "In conclusion, CCL28, as a chemokine induced by tumor hypoxia, could promote angiogenesis in lung adenocarcinoma through targeting CCR3 on microvascular endothelial cells." (PMID 27250766, 2016). "However, in the present study, the expression of CCR3 was identified in the microvascular endothelial cells of lung adenocarcinoma, which could be directly affected by CCL28." (PMID 27250766, 2016). "Besides other effects on tumor biology, such as immunosuppression, CCL28 could promote angiogenesis in lung adenocarcinoma by directly activating its receptor, CCR3, on microvascular endothelial cells." (PMID 27250766, 2016). "We analyzed adjacent sections of paraffin embedded lung adenocarcinoma samples (n = 27) by immunohistochemistry with antibodies against CD34, CCR3 and CCR10." (PMID 27250766, 2016). "CCR3, receptor of CCL28, was highly expressed in vascular endothelial cells in lung adenocarcinoma when examining by immunohistochemistry." (PMID 27250766, 2016). "Taken together, the evidences indicated that CCR3, but not CCR10, was the main receptor of CCL28 on the microvascular endothelial cells, especially in lung adenocarcinoma." (PMID 27250766, 2016).
lung diseases (3 papers, 2021 to 2024). "Further verification was done by qPCR as we tested five differential peak-related genes (Rras2, Ttll12, Ccr3, Ccr6 and Trps1) with known contributions to lung diseases." (PMID 33902609, 2021).
osteoporosis (3 papers, 2012 to 2021). A condition of reduced bone mass, with decreased cortical thickness and a decrease in the number and size of the trabeculae of cancellous bone (but normal chemical composition), resulting in increased fracture incidence. "In addition, it has been demonstrated that overexpression of CCR3 increases the recruitment of circulating monocytes in bone, enhances monocyte differentiation into osteoclasts, and eventually promotes the development of osteoporosis." (PMID 34488536, 2021).
ovarian tumors (3 papers, 2018 to 2020). "Protein expression of markers of basophils (CCR3, CD123, FcεRI) and basophil activation (CD63, CD203c, tryptase) were identified in a proportion of ovarian tumors by IHC analyses." (PMID 32645919, 2020). "Protein and gene expression analyses support the presence of basophils (CCR3, CD123, FcεRI) and activated basophils (CD63, CD203c, tryptase) in ovarian tumors." (PMID 32645919, 2020).